AIPL1 (AIP like 1 HSP90 co-chaperone)
Description:
May be important in protein trafficking and/or protein folding and stabilization.
Synonyms: AIPL2; LCA4
Tractability: Small molecule: a structure with a bound ligand is known. PROTAC: ubiquitination databases record sites on it.
Gene: Protein-coding gene on chromosome 17 (6,393,693 to 6,435,199, reverse strand). Ensembl gene ENSG00000129221.
Subcellular location: Cytoplasm; Nucleus
Subcellular location (Human Protein Atlas): Nuclear speckles; Cytosol
Gene Ontology:
Molecular function: farnesylated protein binding; protein binding; peptidyl-prolyl cis-trans isomerase activity
Biological process: protein farnesylation; visual perception
Cellular component: cytoplasm; nucleus; photoreceptor inner segment
Genetic constraint (gnomAD): Loss-of-function variants: 25 observed, 34.57 expected, observed/expected ratio (o/e) 0.72, 90% interval 0.53 to 1.01. The upper end of that interval is the gene's LOEUF score, 1.01, which puts it in group 4 of 6, group 1 being the genes least tolerant of losing a copy. Missense variants: 485 observed, 511.05 expected, observed/expected ratio (o/e) 0.95, 90% interval 0.88 to 1.02. Synonymous variants: 210 observed, 212.17 expected, observed/expected ratio (o/e) 0.99, 90% interval 0.88 to 1.11.
Gene-disease validity (ClinGen):
ClinGen rates the evidence that AIPL1 causes each of these diseases.
AIPL1-related retinopathy (autosomal recessive): Definitive. A retinopathy caused by biallelic variants in the AIPL1 gene.
inherited retinal dystrophy (autosomal dominant): Disputed. An instance of retinal degeneration that is caused by an inherited modification of the individual's genome.
Homologues: Orthologues: chimpanzee AIPL1 (99% identical), macaque AIPL1 (96% identical), guinea pig AIPL1 (78% identical), pig AIPL1 (78% identical), rat Aipl1 (75% identical), mouse Aipl1 (74% identical), dog AIPL1 (62% identical), tropical clawed frog aipl1 (61% identical), rabbit AIPL1 (60% identical), zebrafish aipl1 (57% identical), Drosophila melanogaster CG1847 (32% identical), Caenorhabditis elegans aipr-1 (28% identical). Paralogues in human: AIP (42% identical).
Diseases named in the same sentence as AIPL1 in open-access papers:
AIPL1 is named in the same sentence as 34 diseases in open-access papers, as found by Europe PMC text mining. Sharing a sentence is not in itself a finding about the gene and the disease. The quoted sentences say what the papers report.
Leber congenital amaurosis (30 papers, 2008 to 2025). Leber congenital amaurosis (LCA) is a retinal dystrophy defined by blindness and responses to electrophysiological stimulation (Ganzfeld electroretinogram (ERG)) below threshold, associated with severe visual impairment within the first year of life. "Mutations affecting the expression of PDE6 and AIPL1 cause retinitis pigmentosa and Leber congenital amaurosis with associated photoreceptor degeneration." (PMID 37172722, 2023). "Mutations in AIPL1 lead to a severe form of Leber congenital amaurosis, a major cause of blindness in children." (PMID 35065964, 2022). "Defects in PDE6 and AIPL1 underlie several severe retinal diseases, including retinitis pigmentosa and Leber congenital amaurosis." (PMID 35065964, 2022). "Mutations in AIPL1 are associated with Leber congenital amaurosis, a severe form of inherited retinal degeneration." (PMID 34957217, 2021). "Delivery of miR-204 exerted neuroprotective effects also in a mouse model of Leber congenital amaurosis, due to mutations of the Aipl1 gene." (PMID 31837604, 2020). "In fact, mutations in the TPR containing protein aryl-hydrocarbon-interacting-protein-like 1 (AIPL1) results in Leber congenital amaurosis, one of the most severe inherited retinopathies." (PMID 32629961, 2020). "Aryl hydrocarbon receptor (AhR)-interacting protein-like 1 (AIPL1) was first discovered in association with Leber congenital amaurosis (LCA)." (PMID 31344897, 2019). "Mutations in the AIPL1-encoding gene were identified as one of the factors causing Leber congenital amaurosis (LCA), an autosomal recessive inherited retinopathy leading to blindness in early childhood." (PMID 30568592, 2018). "Genetic mutations in aryl hydrocarbon receptor interacting protein-like 1 (AIPL1) cause photoreceptor degeneration associated with Leber congenital amaurosis 4 (LCA4) in human patients." (PMID 28378769, 2017). "Mutations in the AIPL1 gene cause the devastating disease Leber’s congenital amaurosis (LCA), which is characterized by profound visual impairment or loss at birth." (PMID 25799540, 2015). "Mutations in the retina and pineal-specific aryl hydrocarbon receptor interacting protein-like 1 (AIPL1) lead to the inherited blindness Leber congenital amaurosis (LCA), which is characterised by severe vision loss or blindness at birth." (PMID 22347407, 2012). "Mutations in AIPL1 cause the inherited blindness Leber congenital amaurosis (LCA)." (PMID 22347407, 2012). "In fact, recent reports show that AAV8 has been used to drive therapeutic expression in and restore function to photoreceptors in several models of inherited retinal degeneration, including Leber congenital amaurosis (AIPL1 and RPGRIP forms) and X-linked juvenile retinoschisis." (PMID 21552473, 2011). "The aim of this study was to investigate the interaction and co-localization of novel interacting proteins with the Leber congenital amaurosis (LCA) associated protein aryl hydrocarbon receptor interacting protein-like 1 (AIPL1)." (PMID 25799540, 2015). "Mutations in AIPL1 cause Leber congenital amaurosis (LCA), a severe early onset retinopathy and AIPL1 functions as a chaperone specific for PDE biosynthesis." (PMID 24301679, 2014). "A milestone was achieved in 2025 with the treatment of children with Leber congenital amaurosis (LCA) using intravitreal injection of an AAV vector carrying the AIPL1 gene." (PMID 41155120, 2025). "Leber congenital amaurosis (LCA) is a severe inherited retinal disorder manifesting at birth or in early infancy, with a subset of cases linked to mutations in the aryl hydrocarbon receptor-interacting protein-like 1 (AIPL1) gene." (PMID 41465493, 2025). "To study the effectiveness of gene perturbations in HF-iCas9 stem cells, we targeted several genes linked to Leber congenital amaurosis (LCA), a rare childhood-onset retinal dystrophy caused by mutations in the AIPL1, CRB1, and RPGRIP1 genes, among others." (PMID 36553630, 2022).
Leber congenital amaurosis (continued). "A two-year-old boy in Family 40 had Leber congenital amaurosis (LCA), and his parents were heterozygous carriers of an AIPL1 variant." (PMID 33781268, 2021). "Biallelic variants in the AIPL1 gene are predominantly associated with autosomal recessive Leber congenital amaurosis (LCA), a congenital-onset, rapid and progressive retinal degeneration leading to the severe impairment or loss of vision within the first few years of life." (PMID 33067476, 2020). "Further, mutations in the gene encoding AIPL1 cause Leber congenital amaurosis (LCA)." (PMID 32426353, 2020). "AIPL1, a possible AIP subtype showing 49% identity to AIP and is associated with Leber congenital amaurosis, is essential for biosynthesis of retinal rod cGMP phosphodiesterase." (PMID 18334952, 2008). "Children with Leber congenital amaurosis (LCA) carry a disproportionate risk: a masked school survey found KC in 29% of LCA pupils, and 25% of those with biallelic AIPL1 variants develop KC during childhood, likely amplified by the oculo-digital eye-rubbing phenomenon." (PMID 41010702, 2025). "Missense and nonsense variants in the FKBP-like and tetratricopeptide repeat domains of AIPL1 cause Leber congenital amaurosis due to both the absence of HSP90 interaction and the impairment of PDE6 activity." (PMID 39125773, 2024). "The list included genes associated with different forms of Leber congenital amaurosis, involved in disruptions in phototransduction (AIPL1), retinoid cycle (RDH12, RPE65), and transport across the photoreceptor connecting cilium (LCA5), as well as genes evidently interacting with AIPL1 (NUB1, AHR)." (PMID 38203368, 2023). "Mice lacking AIPL1 serve as a disease model of Leber congenital amaurosis." (PMID 34957217, 2021). "NUB1L also interacts with the aryl hydrocarbon receptor interacting protein-like 1 (AIPL1), whose mutations lead to the inherited blindness Leber congenital amaurosis (LCA) and abolishes its interaction with NUB1L, suggesting that NUB1L could be involved in the pathogenesis of LCA." (PMID 28099510, 2017).
retinal degeneration (13 papers, 2011 to 2025). Degeneration of the retina. "Retinal phenotypes in mice with an AIPL1 mutation were studied as an animal model for human AIPL1-caused retinal degeneration." (PMID 41465493, 2025). "This mutation causes early and severe progressive photoreceptor loss, with retinal degeneration occurring prior to adulthood and leading to blindness, making these cats a useful model of AIPL1-associated LCA." (PMID 41465493, 2025). "Of the five IRD genes with significant effects, three (Aipl1, Pde6a, Pde6b) are associated with a recessive retinal degeneration in humans." (PMID 41282224, 2025). "A wide spectrum of mutations in AIPL1 is associated with varying severities of retinal degeneration, implicating diverse pathogenic mechanisms." (PMID 41465493, 2025). "We also report a novel disease-causing variant in AIPL1, c.666G>A (p.W222X), causing severe retinal degeneration and early loss of vision." (PMID 33067476, 2020). "AIPL1 (aryl-hydrocarbon-interacting protein-like 1) mutations are associated with LCA4, a severe early-onset retinal degeneration." (PMID 25650393, 2015). "Case studies show that mutations associated with retinal degeneration of a wide spectrum of severity occur in the exon 3 and in vitro assays support the indispensability of this region for AIPL1 function." (PMID 41465493, 2025). "Retinal degeneration caused by AIPL1 defects has been described in several mouse models of LCA4." (PMID 41465493, 2025). "The previously cited genes could not explain the hereditary pattern of retinal dystrophy affecting the patient (choroideremia is an X-linked disease and AIPL1 is related to recessive forms of retinal degenerations), and cerebellar atrophy is of unknown origins." (PMID 33374679, 2020). "An early observation in Aipl1 knockout and knockdown mice was the post-transcriptional loss of all three subunits of rod PDE6 prior to the onset of retinal degeneration." (PMID 35883534, 2022). "The high abundance of rod photoreceptors in the mouse retina allowed us to isolate the characteristic features of their transcriptome by comparing the Aipl1 knockout model of retinal degeneration to wild type mice." (PMID 27541351, 2016). "These include TRPM1-congenital stationary night blindness, CRB1-RP, CNM4 Jalili syndrome, retinal degeneration in Usher Syndrome (; NCT05158296; NCT04765345), and other forms of LCA including GUCY2D-LCA (LCA1) and AIPL1-LCA (LCA4)." (PMID 37443335, 2024). "However, reduced expression of AIPL1 in mice resulted in a delay in photoresponse onset and recovery prior to retinal degeneration, whereas in the complete absence of AIPL1, a recordable ERG could not be detected at any age." (PMID 41465493, 2025).
Retinal dystrophy (8 papers, 2012 to 2025). Retinal dystrophy is an abnormality of the retina associated with a hereditary process. "This clinical study involved four children aged 1–3 years with severe retinal dystrophy associated with biallelic pathogenic sequence variants in AIPL1." (PMID 41465493, 2025). "The AIPL1 variant associated with PRA (discovered in the Persian) was the rarest variant associated with retinal dystrophies; this variant was screened in a subset of 2,186 samples (including 5 Persian cats) and not observed at all." (PMID 35709088, 2022). "Mutations in the AIPL1 gene cause a severe inherited retinal dystrophy, Leber congenital amaurosis type 4 (LCA4), that manifests as the loss of vision during the first year of life." (PMID 32214115, 2020). "The present study describes a third model, characterized by a rapidly progressive retinal dystrophy due likely to AIPL1 deficiency." (PMID 27030474, 2016). "Most reported cases of AIPL1-associated disease have an early onset severe retinal dystrophy, which poses challenges with regard to potential treatment." (PMID 22412862, 2012). "For preclinical testing, one of the most suitable models is a feline in vivo model of AIPL1-related retinal dystrophy that has been identified and genetically characterized." (PMID 41465493, 2025). "The disease-associated variants for retinal dystrophies screened in this study include CEP290, KIF3B and AIPL1." (PMID 35709088, 2022).
Leber congenital amaurosis type 4 (7 papers, 2017 to 2025). "Genetic variations in AIPL1 cause type 4 Leber congenital amaurosis (LCA4), which presents as rapid loss of vision in early childhood." (PMID 36982987, 2023). "A similar HDR-based CRISPR/Cas9 strategy was used in order to homozygously correct the biallelic c.834G>A, p.Trp278X mutation with an efficiency of 30% in the AIPL1 gene that causes Leber Congenital Amaurosis type 4 (LCA4)." (PMID 36499601, 2022). "Leber congenital amaurosis type 4 (LCA4), caused by mutations in AIPL1, is one of the most severe early-onset forms of IRD and the cause of congenital loss of vision diagnosed in early childhood." (PMID 41465493, 2025). "Mutations in the aryl hydrocarbon receptor interacting protein-like 1 (AIPL1) gene result in LCA, although individuals heterozygous for a 12-bp deletion were diagnosed with either a dominant form of juvenile retinitis pigmentosa or autosomal dominant cone-rod dystrophy." (PMID 35693295, 2022). "While most cases with mutations in AIPL1 are biallelic, certain mutations may result in dominant cone-rod dystrophy or juvenile retinitis pigmentosa, however, this most probably is not the case for loss of function alleles like the c.834G>A/p.W278* variant in our patient." (PMID 30576320, 2018).
retinal diseases (5 papers, 2020 to 2025). "This comprehensive review summarizes current findings to spark interest and pave the way for further studies in the therapy of AIPL1-caused retinal diseases." (PMID 41465493, 2025). "LCA4 is an inherited retinal disease caused by loss-of-function mutations in AIPL1, leading to the loss of correctly assembled phosphodiesterase 6 (PDE6) enzymes, and subsequent lack of cGMP hydrolysis activity causing cGMP accumulation." (PMID 36982987, 2023). "Disease-causing sequence variants in the highly polymorphic AIPL1 gene are associated with a broad spectrum of inherited retinal diseases ranging from severe autosomal recessive Leber congenital amaurosis to later onset retinitis pigmentosa." (PMID 33067476, 2020). "This study reports the functional assessment of bi- or monoallelic AIPL1 sequence variants, associated with a broad range of retinal diseases, including autosomal recessive LCA and RP, and autosomal dominant CORD and RP." (PMID 33067476, 2020).
Blindness (4 papers, 2012 to 2025). Blindness is the condition of lacking visual perception defined as a profound reduction in visual perception. "Undiagnosed human patients with early-onset blindness should be screened for this AIPL1 variant." (PMID 27030474, 2016). "The proteasome regulator NUB1 was identified as an interacting partner of the inherited blindness protein AIPL1 in a yeast two-hybrid screen, suggesting AIPL1 may influence retinal protein degradation pathways through modulating NUB1 function." (PMID 22347407, 2012). "We hope that the story of AIPL1 is no longer one of irreversible blindness but one of pioneering science successfully bridging the gap between a genetic diagnosis and a transformative therapeutic reality, offering a tangible template for tackling other IRDs." (PMID 41465493, 2025).
retinitis pigmentosa (4 papers, 2020 to 2025). Retinitis pigmentosa (RP) is an inherited retinal dystrophy leading to progressive loss of the photoreceptors and retinal pigment epithelium and resulting in blindness usually after several decades. "Pathogenic mutations in the AIPL1 gene cause severe IRDs, such as LCA4 and some forms of retinitis pigmentosa (RP)." (PMID 41465493, 2025).
keratoconus (3 papers, 2013 to 2025). A degenerative, structural disorder of the eye, characterized by a cone-shaped protrusion of the cornea. "Cataract was reported in two individuals (CRB1, LCA5) and keratoconus was identified in three individuals (AIPL1, CEP290, LCA5), of which two reported eye poking." (PMID 29178642, 2017). "In one patient (LCA81–1) identified with nonsense RPGRIP1 mutation, the clinical diagnosis indicated a cornea plana (lesser K readings suggesting a flater cornea) in contrast to keratoconus, an associated clinical feature of LCA described usually with AIPL1 and CRB1 mutations." (PMID 24066033, 2013).
cone-rod dystrophy (2 papers, 2018 to 2025). Inherited retinal dystrophies that belong to the group of pigmentary retinopathies. "Although mutations in AIPL1 are mainly associated with autosomal recessive LCA and early-onset retinal dystrophy (EOSRD), AIPL1 is also linked to less severe IRDs of cone-rod dystrophy, juvenile or early-onset RP, non-early onset RP, and late-onset retinal degeneration." (PMID 41465493, 2025).
retinoblastoma (2 papers, 2021 to 2025). A malignant tumor that originates in the nuclear layer of the retina. "High endogenous levels of AIPL1 in retinoblastomas, as confirmed by later studies, make them a relevant in vitro system for investigating protein–protein interactions and cellular localization." (PMID 41465493, 2025). "The finding that the level of AIPL1 expression in retinoblastoma cells is comparatively high validates the use of these cancer cell lines for studies of AIPL1 interaction properties." (PMID 41465493, 2025).
Usher syndrome (2 papers, 2020 to 2024). A syndromic diseae characterized by the association of sensorineural deafness (usually congenital) with retinitis pigmentosa and progressive vision loss. "An interesting case is also represented by patient RP_38, who presented disease mutations in a gene causative of Usher Syndrome (USH2A), Bardet-Biedl Syndrome (BBS2), retinitisp (AIPL1) and choroideremia (CHM)." (PMID 33374679, 2020).
congenital nystagmus (1 paper, 2020). Nystagmus present at birth or caused by lesions sustained in utero or at the time of birth. "Severe congenital nystagmus and non-progressive vision loss together with a predicted pathogenic variant in AIPL1 is consistent with the ophthalmologist diagnosis of LCA in the affected individuals of the GCUF01family." (PMID 32976546, 2020).
hyperopia (1 paper, 2025). A refractive error in which rays of light entering the eye parallel to the optic axis are brought to a focus behind the retina, as a result of the eyeball being too short from front to back. "Hyperopia is common in some IRDs including AD BEST1-retinopathy, RS1 and some LCA genotypes (in the current cohort: AIPL1, ALMS1, CEP290, CRB1, CRX, TULP1)." (PMID 41465105, 2025).
neuroblastoma (1 paper, 2015). Neuroblastoma (NB) is the most common solid, extracranial childhood tumor. "EB1 was examined by immunofluorescence microscopy in SK-N-SH neuroblastoma cells following transfection with human AIPL1 (untagged)." (PMID 25799540, 2015). "For this we co-transfected SK-N-SH neuroblastoma cells with full-length human myc-tagged AIPL1 (myc-AIPL1) and full-length human GFP-tagged EB1 (EB1-GFP), EB2 (EB2-GFP) or EB3 (EB3-GFP), respectively." (PMID 25799540, 2015). "EB1 and EB3 were specifically co-immunoprecipitated with AIPL1 from SK-N-SH neuroblastoma cells." (PMID 25799540, 2015). "AIPL1 is expressed specifically and exclusively in the pineal gland and retinal photoreceptors, thereby necessitating the ectopic expression of AIPL1 in neuroblastoma cells which do not express AIPL1 endogenously." (PMID 25799540, 2015).